MMP9 (matrix metallopeptidase 9)
Diseases named in the same sentence as MMP9 in open-access papers (continued):
Sharing a sentence is not in itself a finding about the gene and the disease.
non-small cell lung carcinoma (98 papers, 2001 to 2025). A group of at least three distinct histological types of lung cancer, including non-small cell squamous cell carcinoma, adenocarcinoma, and large cell carcinoma. "Increased expression of MMP9 was associated with poorer outcomes in nasopharyngeal carcinoma patients and together with increased expression of CTHCR1 and MMP7, higher expression of MMP9 was associated with a lower survival rate after surgery in non-small cell lung cancer patients." (PMID 33717164, 2021). "This study aimed to determine tumor MMP-9 expression in non-small-cell lung carcinoma (NSCLC) and whether it is associated with histopathologic factors and has prognostic value to affect overall survival (OS)." (PMID 32944046, 2020). "Recent studies of delta-tocotrienol on non-small cell lung cancer discovered that the anticancer activity induced by delta-tocotrienol is associated with its ability to decrease Notch-1, Hes-1, Survivin, MMP-9, VEGF, and Bcl-XL expressions, with additional decrease of binding activity in NF-κB-DNA." (PMID 25480449, 2014). "Elevated MMP9 levels positively correlate with poor cancer prognosis, suggesting its potential as a marker for breast, colorectal, ovarian, and non-small cell lung cancer." (PMID 40699769, 2025). "In, 2019, it was reported that ethyl pyruvate (EP) reduces MMP9 levels and attenuates the migration and invasion of non-small cell lung cancer (NSCLC) cells by inhibiting the HMGB1/RAGE axis." (PMID 38529373, 2024). "Recently, Hu and Lu demonstrated that c-MYC activates the long noncoding RNA brain cytoplasmic RNA 1 (BCYRN1), which in turn promotes metastasis in non-small-cell lung cancer (NSCLC) by secreting MMP9 and MMP13." (PMID 39338293, 2024). "The proteasome inhibitor bortezomib in combination with the histone deacetylase inhibitor romidepsin inhibited the expression of MMP-2 and MMP-9 in A549 non-small-cell lung cancer (NSCLC) cells." (PMID 38318187, 2024). "Andecaliximab, a recombinant IgG4 monoclonal antibody targeting MMP9, is under development for the treatment different types of diseases, such as rheumatoid arthritis, Crohn’s disease, and non-small cell lung cancer." (PMID 37469874, 2023). "Studies have shown that MMP9 expression is regulated in ovarian cancer, cervical cancer, non-small cell lung cancer and breast cancer, all of which demonstrate a close relationship to cisplatin sensitivity." (PMID 35431936, 2022). "As an inactivated form of 10 kDa propeptide in non-small cell lung cancer, MMP-9 can facilitate secretion of cells." (PMID 32461933, 2020). "Another group confirmed that EEOS reduced MMP-9 and urokinase plasminogen activator activity in non-small cell lung cancer cells (NCI-H460) by inhibiting the PI3K/Akt signalling pathway." (PMID 32102512, 2020). "EEOS reduced vascular endothelial growth factor production and MMP-9 activity in metastatic-induced NCI-H460 non-small cell lung cancer cells by inhibiting the phosphatidylinositol 3-kinase (PI3K)/Akt signaling pathway." (PMID 32102512, 2020). "Combined detection of SNP and enzyme activity between MMP9 and MMP13 are expected to be a potential diagnostic method of non-small cell lung cancer." (PMID 30889876, 2019). "Combined detection of SNP and enzyme activity between MMP9 and MMP13 is expected to be a potential diagnostic method for non-small cell lung cancer." (PMID 30889876, 2019). "miR-26b decreased MIEN1 levels in non-small-cell lung cancer cells, which downregulated the metastasis activity via the NF-κB/MMP-9/VEGF (vascular endothelial growth factor) pathways." (PMID 31581708, 2019). "In non-small-cell lung cancer cells, the number of migrated and invaded cells and the expression of metastasis-supporting proteins MMP9 and MMP13 changed with the regulation of BCYRN1." (PMID 29435146, 2018). "An inverse correlation between KiSS-1 and MMP-9 has been demonstrated also in non-small cell lung cancer (NSCLC) patients." (PMID 29760678, 2018).
non-small cell lung carcinoma (continued). "ADAM15 promotes the migration and invasion of non-small-cell lung cancer cells by increasing the expression of MMP9 and the conversion of pro-MMP9 to active form." (PMID 28260841, 2017). "It has been previously reported that vascular endothelial growth factor (VEGF) and matrix metalloproteinase (MMP)-9 are important for the occurrence and development of non-small cell lung cancer (NSCLC)." (PMID 24396477, 2014). "Increased expressions of S100A4 and MMP-9 are observed in human non-small cell lung cancer (NSCLC) and have significant correlations with clinical and biological behaviour of such cancer cells." (PMID 21970519, 2011). "The aim of this study is to explore the relationship between IL-8, MMP-9 expressions and clinical pathological features of non-small cell lung cancer (NSCLC) patients and evaluate the diagnostic potential of IL-8, MMP-9 as tumor markers." (PMID 20704821, 2010). "Furthermore, in non-small cell lung cancer, MMP-9 levels have been found to correlate with the tumor’s responsiveness to the combined treatment of celecoxib and Erlotinib." (PMID 39994761, 2025). "In addition, overexpression of SLC6A8 promotes proliferation, migration, and invasion of non-small cell lung cancer, accompanied by upregulation of MMP9 and activation of the NOTCH 1 signaling pathway." (PMID 37234174, 2023). "Overexpression of BTG1 inhibited the proliferation, migration and invasion of hepatocytes, thyroid, nasopharynx, esophagus, breast and non-small cell lung cancer cells and induced apoptosis and cell cycle arrest by downregulating the expression of Cyclin D1, Bcl-2 and MMP-9." (PMID 36339000, 2022). "As it was found that elevated MMP9 levels are positively correlated with a poor prognosis in cancer patients, MMP9 has been suggested as a potential marker candidate for such cancers as breast, colorectal, ovarian, and non-small cell lung cancer." (PMID 35406619, 2022). "Similarly, Rab37 represents an anti-metastatic factor in non-small cell lung cancer (NSCLC) by inhibiting matrix metalloproteinase 9 (MMP9) activity both in vitro and in vivo." (PMID 31973201, 2020). "The objective of this study aim to evaluate the serum levels and polymorphisms of MMP-9 and MMP-13 in non-small cell lung cancer patients compared to normal subjects and their correlation to non-small cell lung cancer histopathology findings in Southern Chinese people." (PMID 30889876, 2019). "Increased expression of MMP-9 in patients with non-small cell lung cancer has been reported; therefore, agents suppressing the expression of the MMPs could inhibit cancer cell migration and invasion." (PMID 24901215, 2014). "In non-small cell lung cancer (NSCLC), the invasive and migratory abilities of cancer cells significantly increase after HO-1 overexpression, decrease after HO-1 silencing and correlate with the expression of metastasis-associated protein EGFR, CD147, and MMP9." (PMID 34067625, 2021). "In addition, CTHRC1 induces non-small cell lung cancer invasion by upregulating MMP-7/MMP-9." (PMID 34968391, 2021). "By contrast, in non-small cell lung cancer, serum MMP-9 levels were demonstrated to be higher in patients with metastatic cancer, indicating that detection of the preoperative plasma MMP-9 expression level may serve as an improved marker for tumor progression when compared with serum MMP-9 levels." (PMID 25621068, 2015). "In addition to these reports, gelatinase B/MMP-9 coding region SNPs Arg279Gln and Arg668Gly may represent potential predictors of survival in Chinese patients with non-small cell lung cancer." (PMID 24473089, 2014). "In human non-small cell lung carcinoma A549 cells, ELF4 inhibits the expression of matrix metallopeptidase 9 (MMP9) and IL8 by reducing their promoter activities, thereby repressing tumor growth and invasiveness." (PMID 40083328, 2025).
non-small cell lung carcinoma (continued). "In a recent study, CTHRC1 serves as a prometastatic gene of non-small cell lung cancer, and the invasion and metastasis ability mediated by it were MMP7- and MMP9-dependent." (PMID 33564303, 2021). "In non-small cell lung cancer, high CXCR4 expression enhances cellular motility and invasion via Epidermal Growth Factor Receptors (EGFRs) and Matrix Metallopeptidase 9 (MMP-9)." (PMID 33937018, 2021). "SLBZ-AP improve clinical chemotherapy benefit and quality of life of patients with non-small-cell lung cancer by upregulating the expression of VEGF and MMP-9." (PMID 32655659, 2020). "SNHG12 overexpression promoted cell invasion, migration, and EMT in non-small cell lung cancer via engaging into Slug/ZEB signaling pathway to regulate expression of E-cadherin, matrix metalloproteinase 9 (MMP-9) and vimentin." (PMID 33124951, 2020). "In non-small cell lung cancer, Hu and Lu found c-MYC activated BCYRN1 to promote tumor cell metastasis through up-regulating MMP-9 and MMP-13." (PMID 31652309, 2019). "For example, matrix metalloprotease (MMP) genes such as MMP9, MMP14, and MMP15, which are usually overexpressed in non-small cell lung cancer, also have multiple E2F-binding sites in their promoters, and their expression is regulated by the Rb-E2F pathway." (PMID 26555075, 2015). "For example, MMP9, MMP14, and MMP15 are regulated by the Rb-E2F pathway and co-expressed in non-small cell lung cancer, while MMP2 and MMP9 are co-induced by some other mechanisms." (PMID 23409137, 2013). "In non-small cell lung carcinoma, URG4 expression is correlated with the expression of MMP-9 expression, which is positively correlated in various cohorts of human NSCLC specimens, and NF-κB-activated MMP-9 expression contributes to the URG4-induced invasiveness of NSCLC cell lines." (PMID 37685545, 2023). "Indeed, KDELR2 overexpression promotes the metastatic phenotype in non-small cell lung cancer (NSCLC) by increasing MMP1, MMP2 and MMP9 secretion and thus cell invasive ability." (PMID 35399533, 2022). "Similarly, in non-small cell lung cancer, two studies have demonstrated that SNHG15 knockdown suppresses tumorigenesis by inhibiting the expression of EMT, MMP2, and MMP9 and regulating the miR-486/CDK14 axis." (PMID 33243205, 2020). "Similarly, a study conducted in the A549 human non-small-cell lung carcinoma cell line, FAK-Src, ERK1/2 and β-catenin regulate the expression of MMP-2 and MMP-9." (PMID 31554180, 2019). "Moreover, matrine restrains angiogenesis by reducing the expression of VEGF, EGF, VEGFR1, MMP-9, and MMP-2 in human non-small cell lung cancer (NSCLC) A549 cells and MDA-MB-231 cells." (PMID 31601793, 2019). "Exosomal miR-3157-3p from non-small cell lung carcinoma (NSCLC) cells promotes pre-metastatic niche formation, angiogenesis, and increased vascular permeability by targeting tissue inhibitor of metalloproteinase (TIMP)/KLF2, which regulates the expression of VEGF, MMP2, MMP9, and occludin in ECs." (PMID 40002766, 2025).
rheumatoid arthritis (98 papers, 2006 to 2026). A chronic, systemic autoimmune disorder characterized by inflammation in the synovial membranes and articular surfaces. "There are many associations between MMP-9 and inflammatory diseases, including inflammatory gastrointestinal, inflammatory hepatic, atopic diseases, acute pancreatic failure, and rheumatoid arthritis." (PMID 36289761, 2022). "Extracellular proteolysis was related with and tested for the inflammation-associated protease gelatinase B/MMP-9 in the following diseases: multiple sclerosis, rheumatoid arthritis and diabetes." (PMID 30449890, 2018). "In an in vitro co-culture system, we show that Rev-erb agonist can suppress macrophage transcript levels of select inflammatory genes (IL6, TNFα, CCL2, and MMP9), which are involved in rheumatoid arthritis and implicated in alphavirus-induced joint pathology." (PMID 30568983, 2018). "We found that in patients suffering of periodontal-rheumatoid arthritis association, serum MMP-9 concentrations are significantly higher than in CP, whereas crevicular MMP-9 levels were distinctly elevated than in CP patients, as well." (PMID 25821836, 2015). "The association of MMP-9 with other diseases such as chronic inflammatory autoimmune diseases, including rheumatoid arthritis, Sjögren’s syndrome, idiopathic uveitis and systemic lupus erythematosus has also been reported." (PMID 24179443, 2013). "Thus, the markedly elevated level of IL-6 in rheumatoid arthritis and osteoarthritis sera and synovial fluid would be expected to generate significant MMP-9 to cause the degradation of articular cartilage extracellular matrix proteins." (PMID 27398263, 2016). "It is of interest to note that they also speculated that elevated MMP-9 was associated with connective tissue turnover in rheumatoid arthritis patients." (PMID 27478294, 2016). "Additionally, MMP9 has recently been identified as a biomarker for M1 macrophages, which are implicated in the immune and inflammatory responses associated with the progression of Rheumatoid Arthritis." (PMID 40070835, 2025). "In particular, the inhibitory effects of NaPPS on CTK, MMP-9, NFATc1, c-Fos and AP-1in OC could translate to it beneficial effects in the prevention of osteoporosis and other bone-erosive diseases such as rheumatoid arthritis and bone diseases associated with excessive bone resorption." (PMID 29720166, 2018). "In the rheumatoid arthritis (RA) model, tetramethylpyrazine (40 mg/kg) significantly decreased MMP-9 expression in synovial cells, thereby delaying joint destruction." (PMID 40529488, 2025). "For example, umbelliferone has been demonstrated in rheumatoid arthritis by diminishing the synthesis of proinflammatory factors, including MMP-9 and MMP-2, and by impeding the inflammatory response, invasion, and migration of fibroblast-like synovial cells." (PMID 40166460, 2025). "In rheumatoid arthritis, excessive MMP-9 released from synovial fibroblasts and infiltrating neutrophils accelerates cartilage erosion and promotes progressive joint destruction." (PMID 41304763, 2025). "Synovial fluid of rheumatoid arthritis contains high levels of MMP-9, including its truncated and citrullinated protein forms." (PMID 38491124, 2024). "KLF2 decreases the enrichment of active histone marks H3K9Ac and H4K8Ac and HAT (P300, PCAF) on the MMP‐9 promoter region along with lower migration of activated monocytes to the rheumatoid arthritis sites." (PMID 39263604, 2024). "A prospective cohort study evaluated the association of plasma matrix metalloproteinases (MMPs) with the incidence of interstitial lung disease in patients with rheumatoid arthritis in a large multicenter RA cohort, further supporting the potential pathogenic role of MMP-7 and MMP-9 for RA–ILD." (PMID 38808332, 2024). "MMP-9 is known to play an important role in rheumatoid arthritis and osteoarthritis, contributing to synovial fibroblast survival, proliferation, migration and invasion." (PMID 37927588, 2023).
rheumatoid arthritis (continued). "The contribution of MMP-9 in the progression of several diseases was reported in extracranial arteriovenous malformations (AVMs), rheumatoid arthritis, several neurological diseases and inflammatory processes, cancer, and ischemic stroke." (PMID 37569509, 2023). "The results of previous studies suggest that MMP-9 levels in SF were higher in patients with rheumatoid arthritis compared to osteoarthritis." (PMID 36676791, 2023). "For instance, gallic acid suppresses the levels of cytokines IL-1 and IL-6, chemokines MCP-1 and MCP-3, cyclooxygenase-2 (COX-2), and matrix metalloproteinase-9 (MMP-9) in fibroblast-like synoviocytes in rheumatoid arthritis." (PMID 36235070, 2022). "Among them, Auranofin, which has been used as an anti‐rheumatoid arthritis, antiparasitic and anticancer agent, exerted a salient effect on elevation of miR‐126a‐5p and reduction of mmp9 simultaneously." (PMID 35758549, 2022). "Among the MMP isoforms, MMP-9 regulates cancer invasion, rheumatoid arthritis, and osteoarthritis by degrading extracellular matrix proteins present in the tumor microenvironment and cartilage and promoting angiogenesis." (PMID 35457257, 2022). "Synovial fluids from rheumatoid arthritis contain high levels of MMP-9, including its truncated and citrullinated proteoform." (PMID 34912337, 2021). "The presence of elevated levels of MMP9 is a common feature in autoimmune conditions such as lupus, Sjögren’s syndrome, multiple sclerosis, and rheumatoid arthritis." (PMID 32042069, 2020). "HIF-1α acts as a key regulator during inflammation, increasing pro-inflammatory cytokines (e.g., TNF-α, IL-1β, IL-6, and IL-8), matrix metalloproteinases (e.g., MMP-1, MMP-3, and MMP-9), and pathways of glucose metabolism in rheumatoid arthritis (RA)." (PMID 33374961, 2020). "Research in rheumatoid arthritis has proven that MMP-9 inhibition reduces the production of various inflammatory factors, including IL-8." (PMID 28494217, 2017). "The MMP-9 expression level has been shown to be increased in synovial effusions of rheumatoid arthritis (RA) and inflammatory arthritis (IA) samples." (PMID 24502696, 2014). "Matrix metalloproteinases (MMPs), particularly gelatinase B (MMP-9), play an integral role in leukocyte migration and have been implicated with other chronic inflammatory and autoimmune diseases such as rheumatoid arthritis." (PMID 23724856, 2013). "Since several studies have documented a rise in plasma levels of MMP-9 in cancer, hepatic and lung diseases and rheumatoid arthritis, subjects with a history of these conditions were excluded from this study." (PMID 22259225, 2012). "CypA is also involved in the attraction and migration of monocytes or vascular smooth muscle cells in rheumatoid arthritis and cardiovascular disease by irritating adhesion molecules and regulating MMP9 secretion." (PMID 23031673, 2012). "Anti-Apo A-1 IgG is an independent predictor of major cardiovascular events in rheumatoid arthritis (RA).Positivity for anti-Apo A-1 IgG is associated with higher levels of IL-8, oxidized LDL, and MMP-9.Anti-Apo A-1 IgG induces pro-inflammatory responses in macrophages." (PMID 41179568, 2025). "Matrix metalloproteinases-3 (MMP-3), a member of the matrix metalloproteinases, can degrade extracellular proteoglycans and type IV collagen; activate the activities of MMP-1, MMP-8 and MMP-9; accelerate articular cartilage aging; and exacerbate osteoarthritis (OA) and rheumatoid arthritis (RA)." (PMID 38667174, 2024). "Additionally, MMP-9 plays a key role in the development of inflammatory disorders (e.g. rheumatoid arthritis; RA)." (PMID 39308858, 2024). "For fibroblasts, transforming growth factor (TGF)-β1 or tumor necrosis factor (TNF)-α induction can enhance the expression of MMP2 and MMP9 in fibroblasts, while the endogenous MMP2 and MMP9 contribute to the survival and proliferation of rheumatoid arthritis (RA) synovial fibroblasts." (PMID 37653282, 2023).